SCG2 (secretogranin II)
Diseases named in the same sentence as SCG2 in open-access papers (continued):
Sharing a sentence is not in itself a finding about the gene and the disease.
insulinoma (1 paper, 2018). "The LC/MS data obtained from the two glucagonoma cases (Case 1 pre‐ and post‐treatment, and Case 2), an insulinoma (Case 3) and 62 control samples from healthy individuals were interrogated for glucagon, CHGA, CHGB, SCG2, insulin, c‐peptide, and the internal standard bovine insulin." (PMID 29857350, 2018).
Lymph node metastasis (1 paper, 2021). "A univariate Cox survival analysis based on TCGA database indicated that TNM stage (p = 3.6e-04), Invasion depth (p = 0.031), Lymph node metastasis (p = 0.002), distant metastasis (p = 4.96e-07), and SCG2 expression (p = 0.008) were significant risk factors for overall survival." (PMID 35047505, 2021).
migraine (1 paper, 2019). "Specifically, for migraine: VIP and SCG2 in the NAc, PACAP, SCG1, and proTRH in the PAG, and PENK in the DH; and for OIH: VIP in the NAc, SCG, proSAAS and PACAP in the PAG, and SCG in the TN and DH, were significantly changed between the treated and control groups (p ≤ 0.1) in both cohorts." (PMID 31649062, 2019).
non-small cell lung carcinoma (1 paper, 2019). A group of at least three distinct histological types of lung cancer, including non-small cell squamous cell carcinoma, adenocarcinoma, and large cell carcinoma. "SCG2 is in connection with the alteration of miRNA profiles in A549 human non-small-cell lung cancer cells." (PMID 30972101, 2019).
osteosarcoma (1 paper, 2018). A usually aggressive malignant bone-forming mesenchymal neoplasm, predominantly affecting adolescents and young adults. "Among these DEGs, there were some genes that have not been reported in osteosarcoma, such as KLRC2, SCG2, so these might reveal the novel mechanism of sorafenib inhibition of osteosarcoma." (PMID 29744300, 2018).
parasite infection (1 paper, 2022). "Alternatively, SCG2 and ALK genes associated with coccidian parasite resistance are also actively involved in the MAPK signaling pathway, which has a significant role in immune responses against parasite infection." (PMID 36553445, 2022).
primitive neuroectodermal tumors of the brain (1 paper, 2025). "Secretogranin II (SCG2) has been confirmed to be related to primitive neuroectodermal tumors of the brain, while secretogranin V (SCG5) primarily regulates the secretion of pituitary hormones, preventing the aggregation of secretion proteins linked to certain diseases." (PMID 40608007, 2025).
systemic lupus erythematosus (1 paper, 2023). An autoimmune multi-organ disease typically associated with vasculopathy and autoantibody production. "In the validation set GSE7305, CXCL12, ROBO3, and SCG2 were significantly enriched in immune-related pathways, including cytokine-cytokine receptor interaction, chemokine signaling pathway, leukocyte transendothelial migration, systemic lupus erythematosus, and MAPK signaling pathway." (PMID 38035102, 2023).
tumor (29 papers, 2008 to 2025). "Loss of MUC2, HSPB8, and SCG2 completely disrupted the formation of tumor spheroids in cells expressing ZEB1." (PMID 35440541, 2022). "SCG2 was associated with tumor immune cells infiltration, promoted M2 macrophage polarization, and correlated with immune checkpoint expression in CRC." (PMID 35047505, 2021). "In addition, SCG2 has been implicated as a candidate tumor suppressor in several tumors." (PMID 34160138, 2021). "The present study further clarified the effects of compound 27 on the expression of DUSP5 and SCG2 in tumor cells after treatment by a combination of RNA-seq and RT-qPCR." (PMID 40473811, 2025). "In tumor tissues, SCG2 upregulation may promote the polarization of M0 macrophages to M2 macrophages and their subsequent differentiation into tumor-associated macrophages, enhancing tumor cell invasion and metastasis and angiogenesis and suppressing immune activity." (PMID 38035102, 2023). "Quantitative PCR results showed that only SCG2 (P <0.001) expression in the tumor was markedly higher than that in adjacent normal tissues." (PMID 35844556, 2022). "Mechanistically, SCG2 inhibits tumor growth and angiogenesis by disrupting the activities of HIF-1α/VEGF in malignant CRC tissues." (PMID 35836930, 2022). "Then, to further validate the key events leading to tumor development, we analyzed the correlation between SCG2 expression and clinicopathological variables." (PMID 36057262, 2022). "To further investigate the immune signature of SCG2, we first scored immune cells in tumor tissues from 539 patients with ccRCC." (PMID 36057262, 2022). "Among these differentially increased IAGs, combined with screening conditions such as fraction genome altered >0.1, and total mutation number >5, we finally identified the most likely potential tumor antigen: SCG2." (PMID 36057262, 2022). "In this study, the regulatory role of SCG2 in tumor angiogenesis in relation to cytokine excretion by tumor cells was investigated rather than solely focusing on the direct role of SCG in endothelial cells." (PMID 34160138, 2021). "The results of the present study suggest that expression of SCG2 protein in tumor cells is a positive prognostic predictor of CRC patients." (PMID 34160138, 2021). "In summary, SCG2 played a critical role in the regulation of tumor immunity and made it a potential biomarker and therapeutic target in CRC." (PMID 35047505, 2021). "The results of an animal study showed that ectopic expression of SCG2 significantly inhibited CRC tumor growth by disrupting angiogenesis." (PMID 34160138, 2021). "The results showed that ectopic expression of SCG2 significantly inhibited CRC tumor growth in mice." (PMID 34160138, 2021). "Rescuing of VEGF in conditioned medium from SCG‐overexpressed cells efficiently blocked the SCG2‐induced inhibition of tumor angiogenesis." (PMID 34160138, 2021). "The results of the present study demonstrated an inhibitory role of SCG2 in tumor angiogenesis, which is inconsistent with the findings of previous studies." (PMID 34160138, 2021). "Next, the potential regulatory role of SCG2 in tumor angiogenesis was investigated by IHC staining of CD31." (PMID 34160138, 2021). "Prognosis analysis indicated that higher expression of SCG2 in tumor cells was correlated with longer disease‐free and overall survival, which is inconsistent with the results of previous studies." (PMID 34160138, 2021). "Correlation analysis indicated that in CRC tumor tissues, SCG2 expression was inversely correlated with HIF‐1α expression (r = −0.6229) as well as VEGF expression (r = −0.6321)." (PMID 34160138, 2021). "The expression and distribution of SCG2 protein in tumor and adjacent tissues were monitored by immunofluorescence microscopy." (PMID 35047505, 2021). "The correlations between SCG2 expression and immune checkpoint genes indicated a potential mechanism of SCG2 regulation on T cell exhaustion and provided a new target for tumor immunotherapy." (PMID 35047505, 2021).
tumor (continued). "In normal tissues, SCG2 was mainly distributed in colonic glands, possibly related to intestinal fluid secretion, whereas in tumor tissues, the intestinal mucosal tissues were destroyed and SCG2 expression decreased." (PMID 35047505, 2021). "Analysis of clinical samples demonstrated that SCG2 was downregulated in CRC tumor tissues, whereas high SCG2 expression was correlated with a good prognosis of CRC patients." (PMID 34160138, 2021). "The results revealed that ectopic expression of SCG2 in tumor cells significantly inhibited tumor angiogenesis in mice." (PMID 34160138, 2021). "SCG2 impaired tumor growth and angiogenesis by inhibiting vascular endothelial growth factor expression and promoting hypoxia‐inducible factor‐1α degradation." (PMID 34160138, 2021). "The identified role of SCG2 in tumor angiogenesis provided multiple angles of evidence of the role of SCG2 in angiogenesis." (PMID 34160138, 2021). "Specifically, in the present study, expression of SCG2 protein was quantified in tumor cells, whereas in the cited previous studies, expression was measured in total cells." (PMID 34160138, 2021). "In contrast, in tumor tissues, the intestinal mucosal tissues were destroyed and total SCG2 expression was decreased." (PMID 35047505, 2021). "The three most highly overexpressed genes: SCG3 (26.6 fold), SCG2 (15.3 fold) and DDC (9.6 fold), have previously been shown to be linked to NE tumour biology, thus confirming the reliability of our study design." (PMID 18827820, 2008). "Hence, it has been revealed that ectopic expression of SCG2 apparently impeded tumor growth by disrupting angiogenesis." (PMID 37588219, 2024). "In addition, higher expression of SCG2 impaired tumor growth and angiogenesis by promoting the degradation of hypoxia-inducible factor-1α in CRC." (PMID 35602610, 2022). "It suggests that the tumor microenvironment in the high SCG2-expressing group may incline to be immune hot compared to the low expression group." (PMID 35844556, 2022). "Integrative analysis of biological pathways hints that SCG2 may be engaged in meditating tumor growth and invasion." (PMID 35844556, 2022). "Furthermore, we found increased expression of the differentiation marker SCG2 in the ex vivo TH-MYCN tumor sphere model after inhibition of fatty acid synthesis." (PMID 33659885, 2021). "SCG2 expression was remarkably decreased in tumor tissues compared with normal tissues of CRC." (PMID 35047505, 2021). "In this study, the potential function of SCG2 in CRC tumor growth was investigated." (PMID 34160138, 2021). "Treatment with SCG2 protein had a therapeutic effect on CRC tumor growth." (PMID 34160138, 2021). "Collectively, ectopic expression SCG2 in CRC cells significantly inhibited tumor angiogenesis." (PMID 34160138, 2021). "Similarly, confocal immunofluorescence microscopy showed SCG2 had an apparent colocalization with macrophages in tumor tissues." (PMID 35047505, 2021). "Ectopic SCG2 expression significantly inhibited CRC tumor growth by disrupting tumor angiogenesis." (PMID 34160138, 2021). "SCG2 might regulate multiple tumor- and immune-related pathways in CRC, influence tumor immunity by regulating infiltration of immune cells and macrophage polarization in CRC." (PMID 35047505, 2021). "In summary, the results of this study clarified the function and mechanism of SCG2 in the regulation of CRC tumor growth, which may provide a potential therapeutic target and a prognostic predictor." (PMID 34160138, 2021). "However, the relationship between SCG2 and tumor immunity of CRC is largely unknown, and the mechanisms underlying it remain to be intensively investigated." (PMID 35047505, 2021). "However, given the tissue specificity, the role of SCG2 likely differs among different tumor types." (PMID 34160138, 2021).
tumor (continued). "PPI analysis indicated that the levels of the mRNAs encoding RBPJ, SKP1, CTNNB1, CDH2, SCG2, VGF, and TFF3 were significantly increased in PanNEN tumor tissues compared with the matched paratumor tissues and may be involved in the DNER signaling pathway in PanNENs." (PMID 33329729, 2020). "There were 253 genes (13.6%) that had decreased expression shared across tumor types, including NPTXR, SCG2, B4GAT1, and ATRN." (PMID 36909536, 2023). "The profiled tumor cells expressed most general PNEC markers (e.g. SCG5, CHGB, SCG2, PCSK1N, CHGA, SCG3) indicating retention of PNEC identity." (PMID 36469459, 2022). "The results showed that SCG2 expression was significantly decreased in CRC tumor tissues, and differentially distributed between tumor and adjacent normal tissues." (PMID 35047505, 2021). "SCG2 was colocalized with macrophages in tumor tissues, whereas there was no apparent colocalization in normal tissues." (PMID 35047505, 2021). "Besides, SCG2 is a stroma-related gene in CRC, its potential function in regulating tumor immune infiltration of CRC needs to be fully elucidated." (PMID 35047505, 2021). "Also, we identified NCAM1, CNTN1, SCG2, CADM1, IL-8, NPTX1, and APOD as PSCB in the tumor secretome." (PMID 31455042, 2019). "All the NE tumour cell lines express a high level of SCG2, whereas the expression level in the non-NE cell group is almost undetectable." (PMID 18827820, 2008). "The results indicated that treatment with the SCG2 protein dramatically inhibited SW620 tumor growth as compared with the controls (IgG) by 64.7% in tumor volume (419.6 ± 91.0 vs. 1190.2 ± 163.7 mm3, respectively) and by 64.3% in tumor weight (0.38 ± 0.05 vs. 1.08 ± 0.12 g, respectively)." (PMID 34160138, 2021). "In the present study, SCG2 protein expression was determined in 270 malignant tissues of CRC patients who were divided into two groups based on expression levels of SCG2 protein in tumor cells, but not in stromal cells." (PMID 34160138, 2021). "In the current investigation, we observed that the SCG2 high expression group was featured by immune activation concomitant with immunosuppression; this characterization describes why immune activation was abundant in the SCG2 high expression group without impeding tumor progression." (PMID 35844556, 2022). "The three most highly overexpressed genes in the NE vs the non-NE tumour cell group (SCG3, SCG2 and DDC), have all previously been described in the context of NE tumour biology, thus confirming the reliability of our study design." (PMID 18827820, 2008).
cancer (23 papers, 2010 to 2025). A tumor composed of atypical neoplastic, often pleomorphic cells that invade other tissues. "We were shocked to learn that all three immunologic activation genes (CXCL10, RXRG, and SCG2) have been linked to cancer progression." (PMID 36685954, 2022). "Furthermore, the association of Tregs and cancer-associated fibroblasts (CAFs) with SCG2 in various tumors was assessed by multiple algorithms." (PMID 36057262, 2022). "Some of the significant cancer hallmark terms are epithelial-mesenchymal transition (MSX1, CXCL12, SCG2, SLIT2), KRAS signaling up (F13A1, ADAMDEC1), inflammatory response (CCL5, VIP), IL-6/JAK/STAT3 signaling (CXCL13)." (PMID 35486660, 2022). "On the contrary, cancer cells with SCG2 overexpression demonstrated more aggressive migratory and invasive potential." (PMID 35844556, 2022). "Simultaneously, SCG2 has been proven to be abnormal regulation in the occurrence and development of a variety of malignant tumors." (PMID 36057262, 2022). "To evaluate SCG2 expression in various human cancers, we analyzed TCGA RNA-seq using TIMER database." (PMID 35047505, 2021). "We then assessed SCG2 mRNA expression levels in TCGA and GEO cohorts and found significantly lower SCG2 expression levels in cancer tissues than normal tissues." (PMID 35047505, 2021). "Secretogranin II is widely expressed in diverse organs and tissues, and is deregulated in various cancers." (PMID 34160138, 2021). "THY1, SCG2, and RUNX1 play risk factors in various cancer types." (PMID 35498539, 2022). "SCG2 protein expression was also lower in cancer tissues than adjacent tissues in CPTAC database." (PMID 35047505, 2021). "Also, SCG2 inhibited expression of HIF‐1α in cancer cells by interacting with VHL, a ubiquity‐degrading enzyme of HIF‐1α." (PMID 34160138, 2021). "Nevertheless, the roles of HOXC6, SERPINE1, FABP4, SCG2, and CALB2 in tumorigenesis, cancer immunity, and ICB treatment are poorly understood." (PMID 35836930, 2022). "Specific shRNAs (sh-Control, sh-SCG2#1/2/3) and SCG2 plasmids were transfected into HCT116 and SW480 cancer cell lines, and the expression of the SCG2 gene was verified by qRT-PCR." (PMID 35844556, 2022). "Based on the correlation between SCG2 and other genes, the GSEA enrichment analysis revealed that SCG2 was involved in cancer invasion and growth signaling pathways." (PMID 35844556, 2022). "By observing the heat map showing the CNV situation, we found that RUNX1, SCG2, and BTG1 have high heterozygous amplification in various cancers, including ACC, TGCT, and UCS." (PMID 35498539, 2022). "Genes in the regulation of the insulin-like growth factor transport pathway have known functions in cancer proliferation and migration, including IGFBP5, PRSS23, SCG2, and SPP1." (PMID 35008167, 2021). "Seven of these predicted proteins (NCAM1, CNTN1, SCG2, CADM1, IL-8, NPTX1, and APOD) were identified in five databases (SignalP 4.1, SecretomeP 2.0, Vesiclepedia, Human Cancer Secretome, and Plasma Proteome), giving support to their relevance in NSCLC." (PMID 31455042, 2019). "On the other hand, the increased candidates included proteins involved in the blockade of cancer cell migration and invasion (SCAI, CARMIL2), autophagy activation (HSBP1, RILP) as well as proteins that can be considered as anti-tumorigenic (SCG2, DIP2A, HSBP1)." (PMID 39833546, 2025). "Some of LINC00094 target PCGs have well‐known functions in cancer, including BATF3, SCG2, and MCM2." (PMID 32460441, 2020). "Moreover, the result from our group about the expressions of ADAM12, AREG, ER, JAGL1, PDGF-A, PN and SCG2 in whole CCA tissues (n = 20) showed that only AREG, PDGF-A and PN had higher level in cancer than those in benign liver tissues with statistical significance (data not shown)." (PMID 20096135, 2010). "However, expression of VHL was not regulated by SCG2 in cancer cells, suggesting that SCG2 may promote the role of HIF‐1α in ubiquity degradation via binding VHL." (PMID 34160138, 2021).
infection (1 paper, 2021). The state of being infected such as from the introduction of a foreign agent such as serum, vaccine, antigenic substance or organism. "After stable infection with lenti‐SCG2, ectopic expression of SCG2 was demonstrated in SW620‐SCG2 and RKO‐SCG2 cells." (PMID 34160138, 2021).
neurodegenerative disease (1 paper, 2020). A disorder of the central nervous system characterized by gradual and progressive loss of neural tissue and neurologic function. "CSF levels of PDYN, SCG2 and VGF were lower in DLB compared to all related neurodegenerative diseases studied (p < 0.05)." (PMID 32552841, 2020). "The combination of VGF, SCG2 and PDYN best differentiated between DLB and related neurodegenerative diseases with acceptable specificity and sensitivity." (PMID 32552841, 2020).
neurodevelopmental disorder (1 paper, 2021). A behavioral and cognitive disorder with onset during the developmental period that involves impaired or aberrant development of intellectual, motor, or social functions. "For the detection of SCG2, a candidate serum biomarker of neurodevelopmental disorder, the nanoplasmonic immunosensor employs an enzyme precipitation reaction combined with a tyramide amplification strategy." (PMID 34815513, 2021). "We examined the serum level of secretogranin II (SCG2) in pediatric patients to evaluate its potential role as a biomarker for neurodevelopmental disorders." (PMID 34815513, 2021). "In conclusion, we developed a highly sensitive nanoplasmonic immunosensor to detect serum SCG2, a candidate biomarker for the early diagnosis of neurodevelopmental disorders." (PMID 34815513, 2021). "The enhanced nanoplasmonic immunosensor (E-NPIS) enabled the detection of serum SCG2 in small volumes of samples to evaluate its potential as a biomarker for neurodevelopmental disorders." (PMID 34815513, 2021). "In the present study, we examined the serum level of SCG2 in pediatric patients using a nanoplasmonic immunosensor to predict its potential role as a biomarker for neurodevelopmental disorders." (PMID 34815513, 2021). "In this respect, the altered SCG2 concentration could serve as a diagnostic indicator for impaired neurodevelopment; thus, we recommend SCG2 as a candidate serum biomarker of neurodevelopmental disorders." (PMID 34815513, 2021). "Thus, the appropriate expression level of SCG2 contributes to normal neurodevelopment, and that any dysregulation in SCG2 expression may induce neurodevelopmental disorders." (PMID 34815513, 2021).